SNORA22B (small nucleolar RNA, H/ACA box 22B)
Gene: Small nucleolar RNA gene on chromosome 7 (56,055,365 to 56,055,502, forward strand). Ensembl gene ENSG00000206603.
Gene Ontology:
Biological process: RNA processing
Cellular component: nucleolus
Homologues: Orthologues: macaque SNORA22B (91% identical), rat Snora22c (85% identical), mouse Gm23245 (84% identical). Paralogues in human: SNORA22 (92% identical), SNORA22C (92% identical).